IL6 (interleukin 6)
Diseases named in the same sentence as IL6 in open-access papers (continued):
Sharing a sentence is not in itself a finding about the gene and the disease.
Thrombocytosis (165 papers, 1998 to 2025). Increased numbers of platelets in the peripheral blood. "The production of hepatic thrombopoietin and subsequent thrombocytosis is caused by elevated levels of thrombopoietin-inducing cytokines, such as interleukin-1 (IL-1), IL-3, IL-11, and tumor-derived IL-6, in tumor-host tissues." (PMID 39941717, 2025). "While several studies have identified IL-6 as a key mediator of cancer-related inflammation and thrombocytosis, its role in GIST-associated syndromes remains largely unexplored." (PMID 40837560, 2025). "Increased production of IL-6 is associated with thrombocytosis, microcytic anaemia, growth retardation, and osteopenia observed in patients with sJIA, and serum IL-6 levels increase/decrease in parallel with the fever spikes." (PMID 39279018, 2024). "Previous research has found that tumor cells cause thrombocytosis by boosting hepatic thrombopoietin (TPO) expression via IL-6 activation." (PMID 36531011, 2022). "In ovarian cancer, thrombocytosis is linked to elevated tumor interleukin-6 and liver-generated thrombopoietin and is associated with shortened overall survival of patients." (PMID 34367949, 2021). "It was suggested that thrombocytosis participates in the progression of RCC by causing elevated interleukin-6 levels, which result in a sustained T helper type 2 cytokine response via stimulating macrophages and T-lymphocytes." (PMID 33350295, 2021). "Inflammatory conditions are a common cause of thrombocytosis and are related to an elevated C-reactive protein or accelerated sedimentation rate as well as elevated pro-inflammatory cytokines such as interleukin-6 (IL-6) and interleukin-11 (IL-11)." (PMID 34945099, 2021). "In subsequent studies, thrombocytosis was found to be caused by IL-6 in Granulocyte-Colony-Stimulating Factor (G-CSF)-producing tumors and by both granulocyte-CSF and IL-6 in Granulocyte Macrophage-Colony-Stimulating Factor (GM-CSF)-producing tumors." (PMID 34722319, 2021). "It has been reported that inflammatory cytokines, such as interleukin-6 (IL-6), are highly associated with thrombocytosis in cancer patients." (PMID 34987523, 2021). "In human samples, ovarian tumor and plasma expression of IL-6 was likewise significantly associated with plasma thrombopoietin levels as well as thrombocytosis." (PMID 33142915, 2020). "High NLR and PLR reflect neutrophilia and thrombocytosis due to the presence of tumour-associated macrophages secreting inflammatory cytokines such as interleukin-6 (IL-6) and IL-17." (PMID 31065387, 2019). "Some proinflammatory cytokines, such as IL-1 and IL-6, also cause megakaryocyte proliferation resulting in thrombocytosis." (PMID 30942057, 2019). "Increasing evidence has demonstrated that Il-6 actively contributes to inflammatory and cancer-associated thrombocytosis through a thrombopoietin (TPO)-dependent mechanism." (PMID 30441823, 2018). "Tumor-derived interleukin-6 was demonstrated as an underlying mechanism of thrombocytosis in cancer, and serum interleukin-6 levels were shown to be 2.4-fold higher in OS than in controls." (PMID 28384168, 2017). "Thrombocytosis associated with malignant disease was, traditionally, attributable to interleukin-6 (IL-6) or to granulocyte-macrophage colony-stimulating factor." (PMID 28465688, 2017). "IL-6 is one of the proinflammatory cytokines that can cause thrombocytosis and change platelet volume." (PMID 26464849, 2014). "This case report, by Jansen and Altmeyer, suggested that the effect of isotretinoin on the PLTs was not clearly understood; however, isotretinoin-induced thrombocytosis can be caused by the effect of IL-6 on the production of PLTs." (PMID 24605049, 2014). "They pointed out the inflammatory response to be greater in PTB patients with thrombocytosis, and this is possibly associated with IL-6." (PMID 23114411, 2012).
Thrombocytosis (continued). "Indeed, among the pro-inflammatory cytokines, IL-6 has been associated with MAS: the ability of IL-6 to mediate platelet responses, including thrombocytosis, platelet hyper-reactivity, and accelerated thrombus formation, has been demonstrated." (PMID 40842478, 2025). "Acute bacterial, viral, or chronic infections (e.g., tuberculosis) may cause secondary thrombocytosis by increasing thrombopoietin synthesis through increased inflammatory component IL-6." (PMID 40528397, 2025). "In carcinoma‐associated thrombocytosis, it is hypothesized that tumor production of IL‐6 directly leads to the generation of hepatic thrombopoietin (TPO), which stimulates megakaryocytic generation of platelets." (PMID 34881459, 2022). "Carcinoma‐associated thrombocytosis involves tumor production of mediators such as interleukin‐6 (IL‐6) and thrombopoietin (TPO) that increase thrombopoiesis and may play a role in tumor evasion and metastasis." (PMID 34881459, 2022). "The cause of malignancy-associated thrombocytosis has been assumed to be attributable to interleukin-6 (IL-6) which potently promotes megakaryocyte maturation and enhances platelet production, although the cellular source of IL-6 may differ between patients." (PMID 25502723, 2015). "The mechanism could relate to paracrine feedback driven by cytokines including interleukin 6, directly causing thrombocytosis." (PMID 21641867, 2011). "The mechanism underlying thrombocytosis is unclear; however, it is speculated to be related to the stimulation of bone-marrow by the cytokines (Interleukin (IL)-1, IL-6, and Macrophage-Colony Stimulating Factor (M-CSF)) secreted from cancer cells." (PMID 20636252, 2010). "The proinflammatory cytokines released in cancer, such as interleukins IL-1, IL-3, and IL-6, can promote the proliferation of megakaryocytes and increase the presence of large platelets, causing their activation and aggregation and possibly leading to the gradual establishment of thrombocytosis." (PMID 36975471, 2023). "However, it is still unclear whether the poor survival of patients with thrombocytosis is caused by IL-6 itself or is a result of IL-6-induced thrombocytosis." (PMID 31362750, 2019). "Recent clinical trials and living meta-analyses in hyperinflammatory conditions confirm that IL-6 blockade is safe and modulates key inflammatory readouts, supporting translational exploration in cytokine-driven thrombocytosis." (PMID 41157266, 2025). "In secondary thrombocytosis, inflammatory compounds (e.g., IL-6) increase thrombopoietin secretion and subsequent megakaryocyte production, increasing platelet count." (PMID 40528397, 2025). "Elevated SII is driven by neutrophilia and thrombocytosis, both of which are common in active TB and mediated by IL-6 and other pro-inflammatory cytokines." (PMID 40572784, 2025). "The release of proinflammatory mediators such as interleukin (IL)-1, IL-3, and IL-6 enhances megakaryocyte proliferation and results in thrombocytosis." (PMID 39831170, 2025). "Regarding the mechanism underlying this relationship, in response to the overproduction of tumor-derived IL-6, the hepatic synthesis of thrombopoietin increases, inducing secondary thrombocytosis." (PMID 39762819, 2025). "In a mouse model, hepatic thrombopoietin synthesis is upregulated in response to tumor-derived IL-6 by the mechanism of paraneoplastic thrombocytosis." (PMID 39941717, 2025). "For instance, systemic inflammation generates the pro-inflammatory cytokine, interleukin-6 (IL-6), which can trigger acute-phase MK production and increased platelet production, also called thrombocytosis." (PMID 41303674, 2025). "IL-6 can also induce megakaryocytosis and thrombocytosis, increased platelet production, which is seen in such patients (platelet counts are typically >500-600k)." (PMID 41357012, 2025).
Thrombocytosis (continued). "Among cytokines, IL-1 has been seen to have a major damaging effect on coronary arteries ECs in KD, whereas IL-6 activates megakaryocyte maturation leading to thrombocytosis." (PMID 39769085, 2024). "The possible mechanism of MPM-related thrombocytosis is that mesothelioma cells persistently secrete interleukin-6, which stimulate thrombopoietin to induce thrombocytosis." (PMID 38267958, 2024). "During the acute phase of IgAV, cytokines such as tumor necrosis factor-α, interleukin-6, and interleukin-8 are significantly increased, leading to thrombocytosis and a more severe disease course." (PMID 37020657, 2023). "Thrombocytosis is explained by the paraneoplastic phenomenon that arises from tumor secretion of the proinflammatory cytokine interleukin-6, which increases thrombopoietin." (PMID 36626395, 2023). "Not all inflammatory markers returned to baseline (CRP↑↑, leukocytosis, thrombocytosis, IL-8↓, IL-6↓)." (PMID 36271425, 2022). "One of the important mediators of thrombocytosis, interleukin-6, is also elevated during the initial phase of ENL." (PMID 35324586, 2022). "The main inflammatory molecules that are active are TNF-α, IL-1 and IL-6, as well as NETs, which partake in the thrombogenesis aspect by inducing thrombocytosis and hyperfibrinogenemia." (PMID 36295093, 2022). "Then, tumor progression and metastasis can be enhanced by thrombocytosis and, in the end, more IL-6 will be released from these tumors, forming a vicious circle." (PMID 36158646, 2022). "IL-6 was increased in DS-TB patients, and evidence suggests that this cytokine promotes thrombocytosis and regulates thrombopoietin levels." (PMID 36325331, 2022). "In tumor-bearing mice, treatment with IL-6 antibody abrogated thrombocytosis and augmented the therapeutic efficacy of paclitaxel." (PMID 34722319, 2021). "Thus, IL-6 inhibitors might be utilized to mitigate cancer-associated thrombocytosis." (PMID 34987523, 2021). "“Inflammaging” is characterized by immunosenescense and thrombocytosis, as well as overproduction of systemic inflammatory cytokines IL-1, TNFα, IL-6, and C-reactive protein (CRP)." (PMID 34502021, 2021). "Early studies showed that overexpression of interleukin-1β (IL-1β) and interleukin-6 (IL-6) in malignant diseases was related to thrombocytosis." (PMID 34722319, 2021). "Certain inflammatory cytokines, mainly interleukin-6, that increase with inflammation have been noted to stimulate thrombopoietin production and induce thrombocytosis." (PMID 32817656, 2020). "Although the mechanism of thrombocytosis is not completely understood, accelerated megakaryopoiesis due to elevated megakaryocytic growth factors such as thrombopoietin, interleukin (IL)-6, or IL-11 has been assumed." (PMID 32181630, 2020). "As for platelets, thrombocytosis is common in cancer because tumor cells secrete thrombopoietic cytokines, such as interleukin-6 (IL-6)." (PMID 32719600, 2020). "Similar to thrombocytosis, IL-6 was also found to correlate with tumor stage, size, metastasis and patient survival in CRC." (PMID 32867390, 2020). "An elegant model proposed by several authors suggests that IL-6 plays a crucial role in inducing cancer-related thrombocytosis, via up-regulation of hepatic TPO transcription." (PMID 31991775, 2020). "The increase of platelet count is due to tumor-secreted cytokines, such as interleukin (IL-6), which plays a role in stimulating the growth of megakaryocytes and thrombocytosis." (PMID 31362750, 2019). "At the same time, inflammatory cytokine, IL-6, can stimulate megakaryocyte growth and induce thrombocytosis." (PMID 31362750, 2019). "The poor survival of patients with thrombocytosis was considered to be a result of IL-6-induced thrombocytosis." (PMID 31362750, 2019). "Although prolonged administration of IL-6 has been shown to induce thrombocytosis, IL-6 and TPO are apparently different and immunologically distinct molecules." (PMID 29666579, 2018).
Thrombocytosis (continued). "Increasing numbers of studies suggested that the proinflammatory cytokines released by tumors, like interleukin-1 (IL-1), interleukin-3 (IL-3), and interleukin-6 (IL-6), can promote megakaryocyte proliferation, and lead to thrombocytosis gradually." (PMID 29179480, 2017). "The release of cytokines such as IL-1, IL-3 and IL-6 in the proinflammatory phase can stimulate the activation of megakaryocytes, which results in thrombocytosis." (PMID 29383181, 2017). "Among these cytokines, IL-6, having multiple functions in many physiological conditions, plays a very important role in the formation of thrombocytosis." (PMID 27833087, 2016). "Bronchial epithelial cells secrete a wide variety of inflammatory cytokines, including IL-1, IL-6, IL-8 and GM-CSF and these cytokines are responsible for the development of thrombocytosis following RSV and HRV infections." (PMID 26965460, 2016). "IL-6 has a potent megakaryocytic effect and has shown to be responsible for thrombocytosis in CSF secreting tumors." (PMID 27866514, 2016). "By stimulating differentiation of megakaryocytes to platelets in the bone marrow, IL-6 induced thrombocytosis in various malignancies." (PMID 27833087, 2016). "In vitro, IL-6 seems to act as a megakaryocyte maturation factor and infusion of IL-6 has been shown to induce modest thrombocytosis." (PMID 24465602, 2014). "High MPV and platelet counts supported reactive (inflammatory) thrombocytosis, in which IL-6-mediated thrombopoietin production stimulates platelet production." (PMID 25402479, 2014). "Injecting a few nanograms per kilogram of IL-1β results in an increase of acute phase proteins, plasma IL-6, neutrophilia and thrombocytosis." (PMID 20175886, 2010). "The relationship between IL-6 and thrombocytosis also was observed in a correlative study in which 83 % of patients with secondary thrombocytosis had elevated serum IL-6 levels." (PMID 19936194, 2008). "We demonstrated a high incidence of thrombocytosis (48%) and a significant correlation between platelet count and the serum IL-6 level." (PMID 9528833, 1998). "Pro-inflammatory cytokines (e.g., IL-1, IL-6) drive thrombocytosis 33, 34, and elevated platelet counts coupled with altered PLR values may reflect both systemic inflammation and tumor microenvironment modulation." (PMID 40740244, 2025). "This temporal consistency supports the hypothesis that IL-6 may be involved in the thrombocytosis observed in GIST." (PMID 40837560, 2025). "GPIba (plasma membrane glycoprotein complex or von Willebrand factor platelet receptor) also regulates the synthesis of thrombopoietin in the liver as part of the acute phase reaction, which is controlled by interleukin 6 (IL-6), and helps stimulate thrombocytosis in systemic inflammation." (PMID 39435166, 2024). "Finally, platelet count also correlates positively with IL-6 (R2 = 0.56), indicating IL-6’s contribution to thrombocytosis in the inflammatory process." (PMID 39469275, 2024). "This might occur as a result of the pro-inflammatory cytokine IL-6, which promotes TPO transcription in the liver and raises TPO blood levels, causing thrombocytosis." (PMID 37228109, 2023). "Taken together, visceral adipose tissue may be an additional source of thrombopoietin and IL-6, which may explain thrombocytosis in patients with high vFMR; however, further studies are needed to prove this." (PMID 36681847, 2023). "Moreover, a rise in thrombopoietin values and IL-6 was observed, which explains the existence of a paracrine circuit where the increase in thrombopoietic cytokines leads to paraneoplastic thrombocytosis, which stimulates tumor growth." (PMID 36837431, 2023). "Tumor cells produce cytokines, such as IL-6, that stimulate thrombocytosis." (PMID 38002048, 2023).
Thrombocytosis (continued). "Combining the effect of thrombocytosis of thrombopoietin and interleukin-6 released by tumour cells, raised platelet counts (opposed to low or normal lymphocyte count) leads to increased PLR and hence worsened oncological outcome in patients as a negative predictor." (PMID 37046847, 2023). "One mechanism that could explain thrombocytosis in many tumors could be tumor-derived interleukin-6 (IL-6), which stimulates thrombopoietin (TPO) production in the liver, thereby promoting megakaryopoiesis and thrombocytosis." (PMID 36901997, 2023). "However, malignant cells trigger the production of myeloid-stimulating cytokines (i.e., interleukin 6, tumor necrosis factor-α, and growth factors) that contribute to thrombocytosis." (PMID 36110962, 2022). "We further hypothesized that dogs with carcinoma and concurrent thrombocytosis would have higher concentrations of IL‐6 and TPO when compared to dogs with carcinoma and normal platelet counts." (PMID 34881459, 2022). "This thrombocytosis (defined as circulating thrombocytes of more than 450.000/mm3) is determined by aberrant paracrine signaling via a high circulating level of interleukin 6 (a by-product of the tumor microenvironment) and thrombopoietin (produced by the liver)." (PMID 35626439, 2022). "This is supported by the evidence that silencing IL-6 and thrombopoietin abrogates thrombocytosis in animal models, and pre-treatment thrombocytosis in patients with EOC tends to be related to advanced stage, higher grade, higher level of CA-125, larger ascites volume, and larger tumor residual." (PMID 36158646, 2022). "Moreover, increased serum IL‐6 concentration has also been associated with other serological abnormalities, such as elevated serum CRP6 and thrombocytosis, as IL‐6 is a major stimulatory factor for hepatocytes and multipotent hematopoietic progenitors." (PMID 34762752, 2022). "In secondary thrombocytosis, interleukin-6 (Il-6) constitutes an additional key mediator." (PMID 33712866, 2021). "In PV patients, high levels of IL-12 are associated with hematocrit; high IL-1β and HGF levels are associated with leukocytosis; low IL-6 and FGF (fibroblast growth factor) levels are associated with hemoglobin concentration; and low GM-CSF levels are associated with thrombocytosis." (PMID 34084749, 2021). "In addition to CRP induction, interleukin-6 also plays a pivotal role in thrombocytosis of inflammation." (PMID 32429293, 2020). "Measurement of IL-1β, IL-6 and Tpo plasma levels at different time points confirmed the etiopathogenetic role of IL-1β in causing the thrombocytosis, while Tpo did not appear to be involved and this explains the excellent response to treatment with Anakinra." (PMID 31234906, 2019). "The inhibition of TPO and Il-6 in tumor-bearing mice was sufficient to reverse thrombocytosis." (PMID 30441823, 2018). "It’s postulated that abnormal cytokine hyperproduction such as interleukin-6 (IL-6) and interleukin-1 (IL-1) may be responsible for the muti-systematic manifestations including thrombocytosis and Castleman’s disease." (PMID 29179528, 2017). "The production of thrombopoietic factors from growing tumors, such as interleukin 1 (IL-1), IL-3, IL-6, IL-11, leukemia inhibitory factor, KitL, and oncostatin M, may be involved in thrombocytosis." (PMID 29163847, 2017). "Tpo in conjunction with IL-6 contributes to the thrombocytosis of patients with Kawasaki disease." (PMID 25006474, 2014). "Indeed, silencing of the IL-6 and thrombopoietin genes markedly abrogated thrombocytosis (and halted tumor progression) in a mouse model of epithelial ovarian cancer." (PMID 25469228, 2014). "It has been hypothesized that, in inflammatory states and malignant diseases, thrombocytosis might be mediated through an IL-6–induced increase in TPO levels." (PMID 25025065, 2014). "Also some proinflammatory cytokines such as IL-1 and IL-6 promote megakaryocyte proliferation resulting in thrombocytosis." (PMID 24968121, 2014).